CDK6 (cyclin dependent kinase 6)
Description:
Serine/threonine-protein kinase involved in the control of the cell cycle and differentiation; promotes G1/S transition. Phosphorylates pRB/RB1 and NPM1. Interacts with D-type G1 cyclins during interphase at G1 to form a pRB/RB1 kinase and controls the entrance into the cell cycle. Involved in initiation and maintenance of cell cycle exit during cell differentiation; prevents cell proliferation and negatively regulates cell differentiation, but is required for the proliferation of specific cell types (e.g. erythroid and hematopoietic cells). Essential for cell proliferation within the dentate gyrus of the hippocampus and the subventricular zone of the lateral ventricles. Required during thymocyte development. Promotes the production of newborn neurons, probably by modulating G1 length. Promotes, at least in astrocytes, changes in patterns of gene expression, changes in the actin cytoskeleton including loss of stress fibers, and enhanced motility during cell differentiation. Prevents myeloid differentiation by interfering with RUNX1 and reducing its transcription transactivation activity, but promotes proliferation of normal myeloid progenitors. Delays senescence. Promotes the proliferation of beta-cells in pancreatic islets of Langerhans. May play a role in the centrosome organization during the cell cycle phases.
Synonyms: PLSTIRE; MCPH12
Tractability: Small molecule: an approved drug acts on it; a structure with a bound ligand is known; a high-quality ligand is known; it has a high-quality binding pocket; it belongs to a druggable protein family. PROTAC: it is named in the literature on targeted protein degradation; ubiquitination databases record sites on it; its protein half-life has been measured; a small molecule that binds it is known.
Target class: CMGC protein kinase group; Protein Kinase; Enzyme; Kinase
Chemical probes: ABEMACICLIB (high quality), BSJ-03-123 (high quality), BSJ-03-204 (high quality), BSJ-04-132 (high quality), CP-10 (high quality), PALBOCICLIB (high quality)
Gene: Protein-coding gene on chromosome 7 (92,604,921 to 92,836,591, reverse strand). Ensembl gene ENSG00000105810.
Subcellular location: Cytoplasm; Nucleus; Cell projection, ruffle; Cytoplasm, cytoskeleton, microtubule organizing center, centrosome
Subcellular location (Human Protein Atlas): Nucleoplasm; Cytosol
Pathways (Reactome):
Cellular responses to stimuli: Oncogene Induced Senescence; Oxidative Stress Induced Senescence; Senescence-Associated Secretory Phenotype (SASP)
Disease: Defective binding of RB1 mutants to E2F1,(E2F2, E2F3); Evasion of Oncogene Induced Senescence Due to Defective p16INK4A binding to CDK4 and CDK6; Evasion of Oxidative Stress Induced Senescence Due to Defective p16INK4A binding to CDK4 and CDK6
Cell Cycle: Cyclin D associated events in G1; Drug-mediated inhibition of CDK4/CDK6 activity
Gene expression (Transcription): Regulation of RUNX1 Expression and Activity
Gene Ontology:
Molecular function: ATP binding; cyclin binding; cyclin-dependent protein serine/threonine kinase activity; FBXO family protein binding; protein binding; kinase activity; protein kinase activity; protein serine kinase activity
Biological process: cell dedifferentiation; gliogenesis; negative regulation of cell cycle; negative regulation of cellular senescence; negative regulation of epithelial cell proliferation; negative regulation of monocyte differentiation; negative regulation of myeloid cell differentiation; negative regulation of osteoblast differentiation; positive regulation of cell-matrix adhesion; positive regulation of fibroblast proliferation; regulation of erythrocyte differentiation; regulation of gene expression; response to virus; type B pancreatic cell development; astrocyte development; dentate gyrus development; G1/S transition of mitotic cell cycle; G2/M transition of mitotic cell cycle; generation of neurons; lateral ventricle development; negative regulation of cell differentiation; negative regulation of cell population proliferation; regulation of cell cycle; regulation of cell motility; DNA damage response; and 2 more
Cellular component: centrosome; cyclin D1-CDK6 complex; cyclin D3-CDK6 complex; cyclin-dependent protein kinase holoenzyme complex; cytoplasm; cytosol; nucleoplasm; nucleus; ruffle; cyclin D2-CDK6 complex
Genetic constraint (gnomAD): Loss-of-function variants: 5 observed, 25.51 expected, observed/expected ratio (o/e) 0.2, 90% interval 0.1 to 0.41. The upper end of that interval is the gene's LOEUF score, 0.41, which puts it in group 1 of 6, group 1 being the genes least tolerant of losing a copy. Missense variants: 190 observed, 351 expected, observed/expected ratio (o/e) 0.54, 90% interval 0.48 to 0.61. Synonymous variants: 136 observed, 144.48 expected, observed/expected ratio (o/e) 0.94, 90% interval 0.82 to 1.09.
Cancer hallmarks: proliferative signalling (promotes)
Homologues: Orthologues: chimpanzee CDK6 (100% identical), guinea pig CDK6 (99% identical), dog CDK6 (98% identical), pig CDK6 (98% identical), rat Cdk6 (97% identical), mouse Cdk6 (96% identical), rabbit CDK6 (89% identical), macaque CDK6 (87% identical), tropical clawed frog cdk6 (87% identical), zebrafish cdk6 (79% identical). Paralogues in human: CDK4 (65% identical), CDK2 (44% identical), CDK3 (43% identical), CDK5 (42% identical), CDK1 (41% identical), CDK13 (40% identical), CDK18 (39% identical), CDK16 (39% identical), CDK17 (39% identical), CDK14 (39% identical), CDK12 (38% identical), CDK11B (37% identical), and 14 more.
Diseases named in the same sentence as CDK6 in open-access papers:
CDK6 is named in the same sentence as 274 diseases in open-access papers, as found by Europe PMC text mining. Sharing a sentence is not in itself a finding about the gene and the disease. The quoted sentences say what the papers report.
breast cancer (252 papers, 2008 to 2026). A primary or metastatic malignant neoplasm involving the breast. "Although rare, loss-of-function mutations in the cadherin superfamily member FAT1 have also been associated with CDK4/6is resistance, potentially due to CDK6 overexpression in ER+ breast cancer patients." (PMID 40244377, 2025). "Recently, growing evidences have demonstrated that CDK6 is closely associated with a variety of human tumors, especially hematologic malignancies, breast cancer and melanoma." (PMID 36457244, 2023). "The A72P at position 4 (TPLH motif) in ANK copy 3 is reported in breast cancer, and loss of CDK6 interaction is reported." (PMID 35056738, 2022). "CDK6 amplification mediated resistance to abemaciclib in breast cancer cells, while elevated CDK6 protein levels were associated with acquired resistance to endocrine treatment." (PMID 35938171, 2022). "In support of the critical roles they played in cell cycle progression, loss of RB1 and upregulation of CDK6 rank on the top hits in driving breast cancer cell evasion from CDK4/6i treatment induced cell cycle blockade." (PMID 34508104, 2021). "An increasing number of studies have shown that the aberrant expression of CDK6 is closely associated with the occurrence and development of many cancers, including breast cancer, ovarian cancer, colon cancer, bladder cancer and more." (PMID 34725345, 2021). "The resistance to paclitaxel caused by LINC00511 was also found in breast cancer and is mediated via regulating miR-29c/CDK6 axis." (PMID 32698787, 2020). "Pharmacological inhibition of either BRD4/FOXO3a association or CDK6 significantly overcomes the resistance of luminal breast cancer cells to AKT inhibitors in vitro and in vivo." (PMID 30518851, 2018). "Finally, we provide evidence of novel CDK6 mutations in breast cancer patients and concordance between experimental and clinical correlates of response to CDK4/6 inhibitors." (PMID 41279360, 2025). "CDK6 overexpression has been linked to reduced sensitivity to CDK4/6is in breast cancer." (PMID 40244377, 2025). "Finally, we find evidence of novel CDK6 mutations in breast cancer patients and concordance between experimental and clinical correlates of response to CDK4/6 inhibitors." (PMID 41279360, 2025). "However, overexpression of CDK6 induced by gene amplification or loss of FAT1 gene functions has been reported to be correlated to CDK4/6 inhibitor resistance in breast cancer cell lines and patient samples." (PMID 35589670, 2022). "CDK6 deficiency has also been linked to breast cancer and melanoma." (PMID 35780240, 2022). "However, acquired resistance to CDK4/6 inhibitors, as observed during breast cancer treatment, is expected and the mechanism involves amplification of CDK6 or loss of function of Rb165,66." (PMID 34893606, 2021). "Moreover, up-regulated CDK6 is associated with the development of several types of cancers, and its high expression confers resistant of treatment in breast cancer cells." (PMID 29502166, 2018). "This is primarily due to the reduction in expression of CDK2, CDK4, CDK6, and Akt proteins, which enhances the sensitivity of resistant breast cancer cells to tamoxifen." (PMID 40283888, 2025). "Using the TCGA database for breast cancer patients (cBioPortal, PanCancer Atlas), we also showed that CDK6 expression significantly correlates with the expression of Met and the TAM RTKs, Axl, MerTK, and Tyro3, and is inversely correlated with HER2." (PMID 38927958, 2024). "Certain targets were enriched in specific cancer types as expected based on the clinical treatment landscape or tumor biology (eg, EGFR, MET, ROS1, MET, and ALK in NSCLC; or ERBB2, CDK4, CDK6, aromatase, and ER in breast cancer)." (PMID 37682776, 2024). "By increasing the inhibitory effects of RB1 on tumor proliferation, CDK4/CDK6 inhibitors have demonstrated efficacy in cancers such as breast cancer." (PMID 39664374, 2024).
breast cancer (continued). "CDK6 protein expression has been recently demonstrated to indirectly predict for sensitivity to CDK4/6 inhibition in ER+ breast cancers, non-small cell lung carcinomas, colorectal carcinomas, and superficial spreading melanomas." (PMID 38066089, 2024). "The overexpression of KNSTRN enhanced the expression of key cell cycle regulators, including CDK4, CDK6, and cyclin D3, thereby accelerating the G1/S phase transition and leading to aberrant proliferation of breast cancer cells." (PMID 38198023, 2024). "From 2015 to 2017, selective inhibitors targeting CDK4 and CDK6 gained US FDA approval for treating breast cancer, including palbociclib, abemaciclib, and ribociclib." (PMID 39184861, 2024). "The other study, examined the c-myc/miR-29b-3p/CDK6 axis, is thought to be responsible for downregulating miR-29b-3p by c-myc to enhance CDK6 activation and induce palbociclib resistance in breast cancer." (PMID 38462658, 2024). "The pharmacological inhibition of CDK6 by palbociclib is one approach for the treatment of breast cancer." (PMID 38731835, 2024). "Using the gene expression database on breast cancer patients, we found that besides CDK6, Met and the TAM RTKs other than Axl are significantly upregulated in TNBC vs. non-TNBC." (PMID 38927958, 2024). "CDK4 is a prominent oncogene in breast cancer, and CDK6 is closely related to the differentiation of human hematopoietic stem cells." (PMID 39011505, 2024). "Several studies have shown that some kinases founded in breast cancer, melanoma and hematopoietic malignancies are able to regulate the function of CDK6 and CDK4, which makes CDK6 an attractive target for therapeutic disruption." (PMID 36457244, 2023). "After treatment with SKACP003, the CDK-4 and CDK-6 genes were significantly downregulated in the breast cancer cell lines compared to the control cell lines, indicating an anti-proliferative activity in all breast cancer cell lines tested." (PMID 36770598, 2023). "LINC00511 can also influence the cytotoxic effects of paclitaxel on breast cancer cells through regulating miR-29c/CDK6 axis." (PMID 37124625, 2023). "CDK4 and CDK6 are not only essential for G1 to S phase cell cycle transition, but also play a central role in the growth of HR+ breast cancer cells." (PMID 37296790, 2023). "After review of the effects of I3C, 50 μM has been shown to inhibit breast cancer cells by 65%, while 200 μM inhibits proliferation by 90%, with significant downregulation of target promoter gene (CDK6) activity being noted." (PMID 37509102, 2023). "CCNI upregulation increased the proliferation of breast cancer cells in vitro and in vivo, with a magnitude similar to that seen upon cyclin D upregulation, an effect that was abrogated by CDK6 silencing or palbociclib treatment." (PMID 37081792, 2023). "Further study showed that YAP-induced CDK6 upregulation was responsible for CDK4/6 inhibitor resistance, highlighting the central role and clinical value of CDK6 in breast cancer therapy." (PMID 37211598, 2023). "According to the results, SKACP003 was able to suppress the expression of CDK-4 and CDK-6 in breast cancer cell lines." (PMID 36770598, 2023). "Several clinical studies on inhibitors targeting CDK4 and CDK6 in pRb-positive tumors (breast cancer, melanoma, liposarcoma, and so on) have shown that the cyclin D–CDK4/6–pRb axis has a significant impact on tumor proliferation and transformation." (PMID 36838737, 2023). "In contrast, the drugs already approved for breast cancer abemaciclib, ribociclib, trilaciclib, and palbociclib bind directly to the protein encoded by the CDK6 gene, cyclin-dependent kinase 6 (CDK6)." (PMID 37965141, 2023). "Some studies have detected CDK6 mRNA expression increases in breast cancer tissues versus that in adjacent tissues." (PMID 36980857, 2023). "CDK4 and CDK6 have shown significant progress in inhibiting metastasis in individuals with metastatic ER+ breast cancer and are now in the adjuvant setting." (PMID 38022130, 2023).
breast cancer (continued). "To date, the United States Food and Drug Administration has approved several CDK6 inhibitors for the treatment of breast cancer and other malignancies." (PMID 35530358, 2022). "CDK6 is able to regulate the cell cycle, and its inhibitors have been used as effective therapeutic drugs for breast cancer." (PMID 36676027, 2022). "Drugs targeting the cell cycle‐regulatory proteins CDK4 and CDK6 have been approved for the treatment of breast cancer, and inhibitors targeting other CDKs are currently in clinical trials." (PMID 35322916, 2022). "Herein, we show that upregulation of CDK6, p-CDK2, and/or cyclin E1 is associated with adaptation and resistance to AI-monotherapy and combined CDK4/6i and ET in ER+ advanced breast cancer." (PMID 36153348, 2022). "CDK4 is an important oncogenic factor in breast cancer and CDK6 plays a role in hematopoietic stem cell differentiation." (PMID 36530984, 2022). "To date, three CDK4/CDK6 inhibitors, palbociclib, ribociclib, and abemaciclib, have been applied in patients with breast cancer." (PMID 35804842, 2022). "For the early G1-to-S-phase cell cycle genes, CDK6 and CCNE1 both showed a strong association with TNBC and basal-like breast cancers in all three cohorts, while CDK2, CDK4 and CCND1 expression were high across all patient samples." (PMID 35884422, 2022). "Several antagonists with excellent activity against CDK4 and CDK6 have been approved for treatment of breast cancer, which restore cell cycle control at the G1/S transition and significantly extend patients' lives." (PMID 35280504, 2022). "Acquired CDK6 amplification has been found to promote breast cancer resistance to CDK4/6 inhibitors." (PMID 35463324, 2022). "Continuous inhibition of CDK4 and CDK6 by abemaciclib resulted in cellular senescence and apoptosis in human breast cancer cells and had broad antitumor activity in human tumor xenograft models." (PMID 34661821, 2022). "PARK2 also decreases the expression of Cyclin-dependent kinase 6 (CDK6) and negatively regulates the proliferation of breast cancer cells." (PMID 35216622, 2022). "Experiments in breast cancer cells suggest that CDK6 fulfils kinase-dependent roles despite p18INK4C binding." (PMID 35326705, 2022). "When 14-3-3 sigma was overexpressed, Western blot assay presented increased protein expression of P21 and decreased levels of cyclin D1, CDK2 and CDK6 in breast cancer cells." (PMID 35890172, 2022). "When used in combination with endocrine therapy, palbociclib, a CDK4 and CDK6 inhibitor, resulted in improved progression-free survival in ERα+/Her2-negative advanced breast cancer." (PMID 35205737, 2022). "CP extract was previously reported to decrease the expression of cyclin D1 and its kinase partner (CDK6) in the hepatoma cell line HepG2 and the breast cancer cell line MCF-7." (PMID 34299510, 2021). "This review is expected to serve as a reference for early and advanced-stage researchers in designing new molecules or repurposing existing molecules as CDK4/CDK6 inhibitors to treat breast cancer." (PMID 34361615, 2021). "Our results also established that inhibition of CK1ε protects hypo-phosphorylated RB1 from degradation and simultaneously abolishes CDK4/6i-induced CDK6 accumulation, thereby providing a potential therapeutic strategy for breast cancer patients." (PMID 34508104, 2021). "Oral highly selective inhibitors of CDK4 and CDK6, such as abemaciclib, represent an important therapeutic advancement in HR+ breast cancer." (PMID 35223458, 2021). "Due to according references with synergistic efficacy of a combined inhibition of PI3K and CDK4/CDK6, e.g. in breast cancer models, manual curation suggested PI3K-inhibition in combination with palbociclib in case of PIK3CA mutation." (PMID 33712636, 2021).